AHR (aryl hydrocarbon receptor)
Diseases named in the same sentence as AHR in open-access papers (continued):
Sharing a sentence is not in itself a finding about the gene and the disease.
infection (continued). "In infections of mice with Citrobacter rodentium, a bacterial pathogen that also infects the gut and induces hyperplasia of enterocytes, knockdown of the AhR gene led to significant weight loss and death, while control animals did not succumb to infection." (PMID 30696739, 2019). "We have already shown that AhR expression was increased during VVC and AhR-deficient mice were more susceptible to the infection." (PMID 31681274, 2019). "They isolated NK cells from Toxoplasma gondii-infected AhR(−/−) mice and found that IL-10 secretion was impaired and associated with increased resistance to such infection." (PMID 29487603, 2018). "This raises concern that pursuing the AHR as a novel therapeutic target carries a risk of unintended adverse consequences, such as poorer ability to fight infection." (PMID 29379138, 2018). "A recent study also reported that the AhR protects against P. aeruginosa infection, as AhR-deficient mice showed increased susceptibility to infection." (PMID 28066767, 2016). "The size of leishmanial lesions in these AhR-deficient mice was significantly increased within the first three weeks after infection but significantly reduced after four weeks." (PMID 24098456, 2013). "In this study we investigated whether prolonged AHR activation is indeed the root cause for detrimental effects in host responses to infection." (PMID 40502009, 2025). "Indeed, loss of AhR in mice results in higher susceptibility to Citrobacter rodentium, which is a mouse model widely used to mimic human infections caused by enteropathogenic and enterohemorrhagic Escherichia coli (E. coli)." (PMID 39767818, 2024). "In addition, indole derivatives can protect intestine against pathogenic infection and limit mucosal inflammation by stimulating IL-22 expression via activating AhR." (PMID 37362931, 2023). "We speculated whether suppression of lung AHR signalling upon infection was caused by alterations in dietary intake or metabolism." (PMID 37587341, 2023). "AhR knock-out mice are susceptible to lethal infection by Cr." (PMID 32230738, 2020). "We show here that HIV-1 Tat protein could associate with AHR and recruit positive transcriptional factors to promote infection." (PMID 31848275, 2019). "Infection efficiencies were tested by X-gal staining for expression of β-gal encoded by the lacZ gene in the control retroviral vector pCMMP-lacZ, and reverse selection for expression of AhR contained in pMFG-AhR." (PMID 19936078, 2007). "The reduced virulence of ΔPf4 despite high levels of pyocyanin production may be explained by our finding that C. elegans mutants unable to sense bacterial pigments through the aryl hydrocarbon receptor are more susceptible to ΔPf4 infection compared to wild-type C. elegans." (PMID 36800381, 2023). "We have developed the following theory regarding the role of the AHR as a sensor to environmental signals: When an individual is exposed to PM, mucosal defense mechanisms and mucociliary clearance of bacteria is altered, leaving the host at increased risk for pathologic infection." (PMID 24349309, 2013). "Taken together, in vitro and in silico results showed that BCoV, a βCoV-like SARS-CoV-2, activates the AhR pathway during infection." (PMID 40142473, 2025). "rodentium Genetically driven constitutive AHR activation improved resistance to infection, whereas prolonged AHR activation by the pollutant TCDD resulted in delayed clearance of C." (PMID 41057229, 2025). "Overall, the different methods used to assess virus yield in CRFK, as well as in A72 cells, all demonstrated that the AhR inhibitor CH223191 significantly reduced FCoV yield during infection." (PMID 40006982, 2025). "During infection, AhR interferes with natural protective immune responses to various microorganisms." (PMID 40006982, 2025). "Overall, our results demonstrated that the AhR inhibitor CH223191 induced a significant reduction in BCoV yield during infection in MDBK cells." (PMID 40142473, 2025).
infection (continued). "Overall, these results suggest that AHR expression during infection in dysbiotic mice is secondary to IDO1 activity, and its activation is involved in inefficient control of the bacterial load associated with dysbiosis." (PMID 40387573, 2025). "The experimental model we studied was infection with the pathogen Citrobacter rodentium as our previous data had shown the importance of AHR in recovery from this infection." (PMID 40502009, 2025). "Cellular lysates collected 48 h post-infection were analyzed by Western blot for AhR and IBV-N protein levels." (PMID 41150072, 2025). "Our results demonstrated that the AhR, expressed in MDBK cells, was upregulated by BCoV infection, and the AhR inhibitor CH223191 induced a significant reduction in both AhR and S expression during infection in MDBK cells." (PMID 40142473, 2025). "The AHR receptor has been shown to play an important role during infection with P. aeruginosa once AHR is activated by P. aeruginosa‐derived pigments and quorum molecules, resulting in improved control of bacterial load." (PMID 40387573, 2025). "Amplifying this response is the aryl hydrocarbon receptor (AhR), a transcriptional regulator activated during infection and inflammation, enhancing Irg1 expression and boosting itaconate production." (PMID 41217188, 2025). "For instance, AhR activation has been reported during infection with mouse hepatitis virus (MHV), MERS-CoV, HCoV229E, SARS-CoV-1, SARS-CoV-2, canine coronavirus (CCoV), porcine epidemic diarrhea virus (PEDV), and feline coronavirus (FCoV)." (PMID 40142473, 2025). "GM-2 and GM-3 were predominantly associated with columnar epithelial responses and included regulators such as ATF2, CDX2, FOXJ2, and AHR, with infection-induced up-regulation of TFs such as SPI1, ESRRA, RFX1, and RARA." (PMID 41042872, 2025). "In the initial stages of infection, ILC3s are activated through ligand-activated transcription factors, including aryl hydrocarbon receptor (AHR), RORγt, and Vitamin A and D receptors or bacteria-derived metabolites (SCFAs, Butyrate)." (PMID 40934190, 2025). "Ahr−/− mice are more susceptible to intestinal challenge and Ahr+/+ mice treated with the AHR agonist exhibited reduced susceptibility to infection." (PMID 40077746, 2025). "Genetically driven constitutive AHR activation improved resistance to infection, whereas prolonged AHR activation by the pollutant TCDD resulted in delayed clearance of C.rodentium associated with a suppression in antibody production." (PMID 40502009, 2025). "This increased susceptibility observed in dysbiotic mice correlates with increased IDO1 enzyme activity and AHR activation, which impair phagocytosis of P. aeruginosa and promote exacerbation of infection." (PMID 40387573, 2025). "Total RNA extracted post-infection was analyzed by qRT-PCR to measure RNA levels of AhR, CYP1A1, and the viral nucleocapsid gene." (PMID 41150072, 2025). "AhR signaling plays an important role in the immune responses of barrier organs, including the lungs, against infection." (PMID 40508196, 2025). "Their work suggests that AHR modulates various regulatory pathways that interact with infection-related signals." (PMID 38932276, 2024). "Research has demonstrated that AhR not only influences CD4+ T cells during infection but also impacts the patterns of DNA methylation in these cells." (PMID 38680494, 2024). "The identification of this mechanism reveals one of the specific ways in which Mtb manipulates T-cell delay in reaching the site of infection and addresses the previous research gap concerning the immunosuppressive effects of AhR on the host." (PMID 39438693, 2024). "Some of these compounds, such as dioxins, activate the Aryl hydrocarbon receptor (AhR) and Pregnane X receptor, both of which are key for intestinal homeostasis and xenobiotic/infection clearance." (PMID 39360551, 2024). "Coronaviruses (CoV) can activate AhR and establish infection through the IDO1-kynurenine-AhR signaling pathway." (PMID 38978778, 2024).
infection (continued). "This review aims to summarize the significant role of AhR in invasive agent infections and its potential as a novel therapeutic target for microbial infections." (PMID 38680494, 2024). "Animal models that enable AHR activity to be quantitatively monitored throughout lifespan and in response to environmental changes including infection, diet and disease, offer important new tools for studying disease pathology and progression." (PMID 38600349, 2024). "The activation of AhR can facilitate the infection of SARS-CoV-2 by upregulating ACE2 expression, in conjunction with an increase in viral nuclear protein (NP) expression." (PMID 38680494, 2024). "A study with mice infected with Trypanosoma cruzi showed that AHR can affect parasite replication and infection." (PMID 39795948, 2024). "AhR primarily promotes the infection of SARS-CoV-2 by inducing the expression of angiotensin-converting enzyme 2 (ACE2) and the secretion of pro-inflammatory cytokines." (PMID 38680494, 2024). "The aryl hydrocarbon receptor (AhR) plays a crucial role in regulating the delicate equilibrium between the fungal-host relationship, commonly referred to as “commensalism vs infection”." (PMID 38680494, 2024). "We will also discuss the mechanisms of widespread involvement of AhR during infection of pathogens, including viruses, bacteria, fungi, and parasites, which can be retrieved until now." (PMID 38680494, 2024). "Accordingly, organs from mice infected with A. baumannii contained elevated levels of CYP1A1 protein, indicating that AHR is activated in vivo following infection with A. baumannii." (PMID 39261458, 2024). "We observed that the combination of BU and VD3 reduced bacterial colonization in liver and spleen, compared to SL1344 infection only, while AhR inhibitor counteracted the combined effects." (PMID 36678175, 2023). "This mode of gene regulation would be consistent with the concept that the AHR is an external sensor of the microbiota that plays an important role in the response to infection, particularly in barrier tissues." (PMID 37755265, 2023). "We observed that the combination of PP and VD3 reduced bacterial colonization (CFU/g tissue) in the liver and spleen, compared to SL1344 infection only, while AhR inhibitor counteracted the combined effects." (PMID 36672703, 2023). "This suggests that the Tph1/5-HT, by sustaining the IDO1 and restraining AhR activation, exerts a critical control upon the dynamic activation of the two pathways in infection." (PMID 37717018, 2023). "In the present report, the effect of the pharmacological modulation of AHR on JUNV in vitro infection was analyzed." (PMID 36851583, 2023). "AhR activates viral transcription and infection by directly binding to the HIV-1 5′ Long terminal repeat (5′-LTR)." (PMID 37744363, 2023). "We also showed that infection with SARS-CoV-2 activates AhR signaling and facilitates viral replication by interfering with IFN-I–driven antiviral immunity and up-regulating ACE2 receptor expression." (PMID 37256962, 2023). "A recent study reported that AhR is activated by infection with SARS-CoV-2 to promote viral replication, suggesting the potentially novel role for AhR modulation as treatment during SARS-CoV-2 infection." (PMID 37256962, 2023). "Taken together, these findings show that protective AHR activity in endothelial cells is regulated by dietary intake, which can be modified by infection status." (PMID 37587341, 2023). "Here, we show that infection with SARS-CoV-2 activates AhR signaling and facilitates viral replication by interfering with IFN-I–driven antiviral immunity and up-regulating ACE2 receptor expression." (PMID 37256962, 2023). "AhR deficiency in mice revealed increased production of pro-inflammatory cytokines (e.g., IL-6 and TNF-α) by macrophages after infection, resulting in higher susceptibility to L. monocytogenes, with higher morbidity and mortality rates." (PMID 36672703, 2023).
infection (continued). "In the B6 model of T. cruzi experimental infection, which is characterized by a higher inflammatory response compared to the Balb/c model, we observed significant differences in the expression of AhR, IDO activity, KYN levels, and Treg cell levels." (PMID 38283348, 2023). "Herein, we report that AhR is expressed in canine fibrosarcoma (A72) cells, where it is considerably activated by infection with genotype II of canine coronavirus (CCoV-II)." (PMID 36366535, 2022). "Herein, OMF induced the activation of AhR in MDBK cells, and, following infection with BoHV-1, a noteworthy activation of AhR in OMF-treated cells was detected." (PMID 35056637, 2022). "AhR activation has been revealed during infection with murine coronavirus (MCoV), Middle East respiratory syndrome coronavirus (MERS-CoV), severe acute respiratory syndrome (SARS-CoV-1), SARS-CoV-2, and human coronavirus (HCoV) 229E." (PMID 36366535, 2022). "The body weight in the C. difficile+pectin+AhR antagonist group was lower than that in the C. difficile+pectin group, indicating that the AhR antagonist exacerbated the infection and clinical symptoms in the pectin diet-fed mice." (PMID 36439215, 2022). "Category I includes 9 modules, representing 62.1% (1305/2102) DE genes in the infection cohorts, but only 30.5% (498/1631) in the AhR antagonist cohorts, 30.6% (1007/3285) in the dsAhR cohorts, and 27.2% (888/3260) in the dsKLF10 cohorts." (PMID 35397616, 2022). "IL-22, secreted by CD3+ T cells and ILC3s in the intestine, has been shown to protect the host from infection as a downstream gene of the AhR pathway." (PMID 36439215, 2022). "The AhR antagonist affected the expression of 696 infection-responsive genes, among them 66 upregulated and 36 downregulated genes had at least twofold differences." (PMID 35397616, 2022). "Aryl hydrocarbon receptor (AhR), a ligand-activated transcription factor, regulates immune homeostasis in the process of infection (Gutiérrez-Vázquez and Quintana, 2018)." (PMID 36299625, 2022). "Based on these findings, herein, we report that AhR, expressed in canine A72 cells, is activated by infection with CCoV-II." (PMID 36366535, 2022). "During post-infection period, the indole pathway and AhR activity were decreased due to a reduction of tryptophol production." (PMID 35090380, 2022). "Regarding all of these findings, it becomes clear that AhR plays a critical role during infection and seems to be important for a well-balanced immune response to invading pathogens." (PMID 35203386, 2022). "During infection, AhR regulates some aspects of the immunity, by interfering with natural protective immune responses to different microorganisms." (PMID 36366535, 2022). "Taken together, our results demonstrated that AhR inhibitor significantly reduced CCoV virus yield during infection in A72 cells." (PMID 36366535, 2022). "To investigate the immune regulatory role of AhR, we pharmacologically manipulated AhR activity and then examined the infection outcomes in mosquitoes upon a bacterial infection." (PMID 35397616, 2022). "Taken together, our preliminary findings show that infection with CCoV activates AhR, and pharmacologic AhR inhibition reduces CCoV replication, identifying AhR as a possible candidate target for CCoV antiviral therapy." (PMID 36366535, 2022). "During infection, NK cells are one of the main sources of IL-10, and AhR activation is required for maximal IL-10 production." (PMID 36110860, 2022). "In conclusion, these findings suggest that the roles of gut microbiota in infection after pectin treatment are partly mediated by the AhR pathway." (PMID 36439215, 2022). "In particular, several mice died due to herpes encephalitis following HSV-1 infection when AhR was up-regulated before infection, whereas, when stimulation of AhR occurred subsequent to HSV-1 infection, herpetic pathology was reduced." (PMID 36421238, 2022).
infection (continued). "In fact, dioxin-treated mice had higher virus titers, and many of them died due to herpes encephalitis if AhR was stimulated before to infection." (PMID 35056637, 2022). "After 24 h of infection, a noticeable reduction in both AhR and NP was detected in the presence of OMF." (PMID 36421238, 2022). "Another group was treated with the AhR antagonist CH223191 (400 μg i.p./mice) on alternate days after infection." (PMID 33936043, 2021). "AHR is a critical mediator of anti-inflammatory responses to infection by bacterial pathogens and of the differentiation and function of immune cells including T cells, innate lymphoid cells, macrophages and DC28." (PMID 34050144, 2021). "Additional physiological functions of the AhR now includes liver development, endotoxin tolerance and resistance to infection." (PMID 33659010, 2021). "IPA analysis suggested increased AHR signaling following infection and identified AHR as a regulator of the transcriptional response." (PMID 34446714, 2021). "In this HSV-1 model, TCDD-treated mice harbored higher virus titers, and many succumbed to herpes encephalitis if AHR was activated before to infection." (PMID 33746961, 2021). "Here we report the identification of AHR signaling as a common host response to infection by multiple CoVs." (PMID 34446714, 2021). "Of note, while IDO-1 drives AHR activation in the context of other infections, MHV induced a similar expression level of downstream genes in wild-type and IDO-1-/- macrophages, suggesting that additional pathways besides IDO-1 are involved in AHR activation." (PMID 33746961, 2021). "We recently showed that AHR activation during infection with Zika or dengue virus suppresses IFN-I-dependent and IFN-I-independent antiviral innate and intrinsic immunity." (PMID 34446714, 2021). "Further, mice treated with either an AHR antagonist or a TDO2 antagonist had fewer FoxP3+ Tregs in the lungs following infection." (PMID 33491663, 2021). "Here we report that AHR is activated by infection with different coronaviruses, potentially impacting antiviral immunity and lung epithelial cells." (PMID 34446714, 2021). "Future studies are needed to further evaluate the potential of AHR antagonists for the treatment of infection by SARS-CoV-2 and other CoVs." (PMID 34446714, 2021). "After 96 h, 2 and 10 weeks of infection lung leukocytes were obtained from infected AhR−/− and WT mice and analyzed by flow cytometry for the presence of intracellular cytokines (IL-12, TNF-α, IL-1β, IL-6, TGF-β and IL-10) in CD11c+ gated cells." (PMID 32647342, 2020). "The pathophysiology of IV infection is related, at least in part, with the imbalance between oxidation and antioxidation systems, as well as with the state of AhR activation." (PMID 32689931, 2020). "I3C acts by protecting the host against Cr-infection by maintaining IL-22 levels and reducing expression of other pro-inflammatory cytokines, likely through an AhR-dependent pathway." (PMID 33076301, 2020). "The lung homogenates of WT and AhR−/− mice were collected after 96 h, 2 and 10 weeks of infection and used to evaluate the presence of cytokines (IL-12, TNF-α, IL-1β, IL-6, IL-23, IL-2, IFN-γ, IL-4, IL-17, IL-22, TGF-β, IL-10, IL-27, and IL-35)." (PMID 32647342, 2020). "The number and phenotype of T cells that were present the lungs of AhR−/− mice and WT controls were evaluated by flow cytometry at weeks 2 and 10 following infection." (PMID 32647342, 2020). "An experiment using Cre/loxP technology confirmed that AhR-mediated iNOS increases and neutrophil migration to the lung during IV infection." (PMID 32689931, 2020). "As AHR has diverse functions in many cell types, including immune cells, endothelial cells, and hepatocytes, its precise role in a given infection is often undefined." (PMID 33021470, 2020). "They showed that conventional DC-derived IL-1β preserves and expands IL-1R1hi IL-22+AhR+ immature NK cells, potentially influencing mucosal innate immunity during infection." (PMID 32647342, 2020).